MEIKIN (meiotic kinetochore factor)
Description:
Key regulator of kinetochore function during meiosis I: required both for mono-orientation of kinetochores on sister chromosomes and protection of centromeric cohesin from separase-mediated cleavage. Acts by facilitating kinetochore mono-orientation during meiosis I, when kinetochores on sister chromosomes face the same direction and are thus captured and pulled by spindle fibers from the same pole. Also required to prevent cleavage of cohesin at centromeres during meiosis I, possibly by acting as a regulator of the shugoshin-dependent protection pathway. Acts in collaboration with PLK1: required for PLK1 enrichment to kinetochores. Not required during meiosis II or mitosis.
Synonyms: SPO13
Gene: Protein-coding gene on chromosome 5 (131,806,990 to 131,945,698, reverse strand). Ensembl gene ENSG00000239642.
Subcellular location: Chromosome, centromere; Chromosome, centromere, kinetochore
Gene Ontology:
Biological process: female meiosis chromosome segregation; homologous chromosome segregation; male meiosis chromosome segregation; meiotic sister chromatid cohesion involved in meiosis I; meiotic sister chromatid cohesion, centromeric
Cellular component: condensed chromosome, centromeric region; kinetochore; chromosome, centromeric region
Homologues: Orthologues: chimpanzee MEIKIN (99% identical), dog MEIKIN (77% identical), pig MEIKIN (76% identical), rabbit MEIKIN (73% identical), mouse Meikin (59% identical), rat Meikin (56% identical).
Diseases named in the same sentence as MEIKIN in open-access papers:
MEIKIN is named in the same sentence as 6 diseases in open-access papers, as found by Europe PMC text mining. Sharing a sentence is not in itself a finding about the gene and the disease. The quoted sentences say what the papers report.
colon cancer (1 paper, 2025). "Moreover, we demonstrated the enriched MEIKIN missense and LoF variants in the distal colon cancer cases in the European-ancestry subset of the UKBB WGS cohort." (PMID 41463182, 2025). "Gene-level analyses identified MEIKIN as a novel EOCRC susceptibility candidate (p value = 1.0 × 10−7), with supporting enrichment of deleterious missense and loss-of-function variants in distal colon cancer cases from the UK Biobank." (PMID 41463182, 2025).
male infertility (1 paper, 2025). The inability of the male to effect fertilization of an ovum after a specified period of unprotected intercourse. "Human GWAS link MEIKIN to venous thromboembolism and basophil count, while murine knockout models exhibit pronounced male infertility, characterized by abnormal spermatogenesis, meiotic defects, and oligozoospermia (as reported by MGI)." (PMID 40869957, 2025).
pituitary tumour (1 paper, 2018). "The genes associated with these terms included histones, pituitary tumour-transforming genes (PTTGs), a meiosis-specific kinetochore protein (MEIKIN) and Centromere Protein W (CENPW)." (PMID 29402920, 2018).
cancer (1 paper, 2025). A tumor composed of atypical neoplastic, often pleomorphic cells that invade other tissues. "Based on STRING analysis, MEIKIN is implicated in chromosome segregation and cell cycle regulation, through interactions with key proteins such as SGO1, SGO2, PLK1, and ESPL1, all of which are known to play critical roles in cancer-associated pathways." (PMID 41463182, 2025).
MEIKIN also shares sentences with these, for which no sentence is quoted: tumor (1 paper); venous thromboembolism (1).